INS (insulin)
Diseases named in the same sentence as INS in open-access papers (continued):
Sharing a sentence is not in itself a finding about the gene and the disease.
Hyperglycemia (continued). "While having promise as an anti-cancer agent, animal studies showed the development of hyperglycemia and reduction of serum insulin upon long-term treatment, effects consistent with the importance of PERK for insulin secretion." (PMID 30931942, 2019). "His hyperglycemia necessitated constant intensive insulin therapy, and he received calcium and vitamin D supplements." (PMID 31574874, 2019). "Blood glucose monitoring showed that the diabetic rats sustained hyperglycemia, while diabetic rats treated with insulin or IT showed a significant decrease in the blood glucose level." (PMID 31583254, 2019). "It has been observed that only a single session of exercise can attenuate hyperglycemia and enhance insulin sensitivity." (PMID 31579613, 2019). "Patients with FCPD present with early disease onset (< 30 years), an associated male preponderance (70%), are underweight, of a low socio-economic status and have severe hyperglycaemia that requires insulin therapy in low doses to achieve euglycaemia." (PMID 30783538, 2019). "Serum TMAO level was positively correlated with serum insulin level and IR in males with hyperglycemia only." (PMID 30972022, 2019). "Procyanidins can prevent postprandial hyperglycaemia through at least two different mechanisms: activation of the insulin-signalling pathway from enhanced GLP-1 secretion and stimulation of AMPK phosphorylation." (PMID 30719284, 2019). "DM is a metabolic disease characterized by hyperglycemia or high glucose (HG) concentrations in blood resulting from defects in insulin secretion, insulin action, or both." (PMID 31815150, 2019). "For example, six guidelines recommended that insulin was the preferred medication for treating hyperglycemia in GDM." (PMID 31196116, 2019). "The extracts modulated glucose metabolism by correcting hyperglycemia or reducing insulin secretion, respectively." (PMID 31398785, 2019). "In our study, lixisenatide ameliorated postprandial hyperglycemia despite a lower increment in insulin concentrations than with placebo." (PMID 30215735, 2019). "In vitro primed BMNCs expressed the β-cell-specific transcription factors, as well as insulin, and improved hyperglycemia and glucose intolerance after transplantation into the streptozotocin-induced diabetic mice." (PMID 30926860, 2019). "Implanted IPCs in the renal subcapsular region were able to secrete functional insulin, confirmed through the presence of serum C-peptide and the reduction of hyperglycemia." (PMID 31109026, 2019). "One animal study with diabetic rats showed that prevention of hyperglycemia by insulin treatment prevented the progression of dental caries." (PMID 30962800, 2019). "Controlled clinical studies have shown increased hyperglycemia and reduced insulin sensitivity during fructose feeding, compared with glucose feeding, although the mechanisms downstream are not well-understood." (PMID 31091299, 2019). "Hypoinsulinemia was caused by the selective, destructive and cytotoxic effect of STZ on the B-cells of rats’ pancreas and hyperglycemia was due to decrement of insulin secretion." (PMID 31516859, 2019). "Conversely, the selective knockout of the AR in mice β-cells was associated with glucose intolerance due to a reduction in glucose-stimulated insulin secretion, leading to hypoinsulinemia, glucose intolerance, and hyperglycemia." (PMID 31817436, 2019). "Insulin treatment rate was similar in all the groups and was only used in case of hyperglycemia during parenteral nutrition." (PMID 30987136, 2019). "For example, central elements of the insulin signaling pathway, PI3K and Akt, were implicated in several studies to conduct the effects of hyperglycemia on cell proliferation." (PMID 31466420, 2019). "They progressively showed overweight, hyperglycemia, -leptinemia, -resistinemia and low insulin and MCP-1 levels compared to NDm offspring." (PMID 31471539, 2019).
Hyperglycemia (continued). "Hyperglycaemia was initially managed with a variable rate intravenous insulin infusion with 2–4 units/h, but hyperglycaemia persisted (capillary blood glucose levels 12–16 mmol/l)." (PMID 31002426, 2019). "The pancreas houses the β cells, which are sensitive to high glucose levels and produce insulin, a strong hormone able to reduce hyperglycemia." (PMID 31623111, 2019). "In zebrafish, cenpx knockdown by morpholino or knockout by CRISPR/Cas9 system ameliorated overfeeding-induced hyperglycemia and upregulated insulin level." (PMID 31417608, 2019). "These pathways are activated by trauma and infections, as well as by insulin depletion and hyperglycemia, leading to accelerated glutathione disposal." (PMID 29300728, 2018). "The preinjection hyperglycemia in T1DM with insulin glargine can be prevented by twice-daily administration of the insulin." (PMID 29508275, 2018). "She persisted with hyperglycemia and high insulin requirements until the discontinuation of cyclophosphamide." (PMID 30526658, 2018). "Chicken is an atypical species in view of their natural hyperglycaemia, insulin resistance, hepatic fatty acid synthesis, and reproductive system." (PMID 30018639, 2018). "Overall, 45% of patients demonstrating hyperglycemia did receive intraoperative insulin therapy (32% of mild, 70% of moderate, and 83% of severe hyperglycemia patients)." (PMID 30025516, 2018). "Typical phenotypes of growth retardation, persistent hyperglycemia, decreased number of insulin-producing β cells and increased number of glucagon-producing α cells were observed in the homozygous PAX4 KO rabbits." (PMID 29950431, 2018). "Infusion of the SST5 analog, however, resulted in a dramatic suppression of insulin secretion, with resulting hyperglycemia, and failure of the β-cells to respond to the amino acid challenge." (PMID 30232095, 2018). "Specifically, overtreatment of hyperglycaemia in older patients is potentially harmful; in particular, insulin and sulfonylureas should be avoided or, if necessary, used with caution." (PMID 29417185, 2018). "Continuous subcutaneous insulin infusion (CSII) is a safe therapy to smooth blood glycemic execution during the management of hyperglycemia either in newly diagnosed or in longstanding T2D patients." (PMID 29651052, 2018). "Several studies have highlighted the use of high concentrations of non-selective SSAO and MAO substrates in stimulating GLUT4 activity, thus reducing hyperglycemia and mimicking insulin effects, including adipocyte differentiation." (PMID 29541060, 2018). "In muscles, metformin reduces hyperglycemia through different mechanisms: by enhancing insulin-stimulated glucose uptake and reducing hepatic glucose output." (PMID 30147674, 2018). "CRS induced the apoptosis of neurons in the anterior part of commissural subnucleus of nucleus tractus solitarius (acNTS) in the hyperglycemic mice, and acNTS mechanical damage also led to insulin-resistant hyperglycemia." (PMID 30618599, 2018). "Additional mechanisms for stress hyperglycemia include impairments in pancreatic beta-cell function with corresponding reduction in insulin secretion." (PMID 30460219, 2018). "DPG-3-2, a component of Ginseng Radix, was shown to lower the blood glucose level and to stimulate the insulin release and biosynthesis in diabetic animals and in pancreas preparations from animals with hyperglycemia." (PMID 30705884, 2018). "Type 2 diabetes (T2D) is a metabolic disorder where insulin-sensitive tissues show reduced sensitivity towards insulin and a decreased glucose uptake (GU), which leads to hyperglycaemia." (PMID 30248999, 2018). "Type 2 DM is a metabolic disease characterised by hyperglycaemia and reduced insulin secretion either because of pancreatic β cell dysfunction or decreased insulin sensitivity." (PMID 29670524, 2018). "Conversely, d-serine reduces glucose stimulated insulin secretion resulting in hyperglycemia and glucose intolerance." (PMID 30093356, 2018).
Hyperglycemia (continued). "An explanation of the relative hyperglycemia induced by isoflurane in C57Bl/6J mice is the impaired release of insulin." (PMID 30199551, 2018). "Taken together, the hyperglycemia observed in the PPT of HFD-fed AnxA6-KO mice was not due to impaired insulin signaling or altered activity of insulin-sensitive transcription factors modulating genes responsible for glycemic control during the PTT." (PMID 30110341, 2018). "Studies on different species of vertebrates seem to suggest that the relationships between food intake control, fat accumulation, insulin resistance, insulin production, hyperglycemia and its pathological effects can evolve differently in different species." (PMID 30151194, 2018). "In such cases, regimens that include Dex induce severe hyperglycemia which requires insulin therapy." (PMID 29454372, 2018). "DM is characterized by hyperglycemia with disturbances in carbohydrate, fat, and lipid metabolism resulting from defects in insulin secretion, insulin action, or both." (PMID 29707032, 2018). "Previous studies report that CTRP9 increased insulin sensitivity and lowered blood sugar levels in the hyperglycemia model." (PMID 30060752, 2018). "In the liver, GCs promote hepatic gluconeogenesis, however, they reduce glucose uptake and utilization in skeletal muscle and white adipose tissue, which coordinately contribute to hyperglycemia and peripheral insulin resistance." (PMID 29568520, 2018). "Certain oral antidiabetic drugs can palliate hyperglycemia via promoting insulin secretion, improving insulin sensitivity in tissues, or reducing the rate of carbohydrate absorption from the gastrointestinal tract." (PMID 30223438, 2018). "Elevation of postprandial blood glucose levels is a major characteristic of GC-DM and insulin is recommended as the drug of choice for the treatment of GC-induced hyperglycemia." (PMID 30285859, 2018). "The increased release of stress hormones during the first hours of acute MI leads to inhibition of insulin secretion and increased insulin resistance, thus inducing stress hyperglycemia." (PMID 29721336, 2018). "Anti-insulin antibodies triggered by viruses and drugs bind to insulin and proinsulin, resulting in initial hyperglycemia and further stimulation of insulin secretion." (PMID 30462811, 2018). "Focusing on insulin secretion, many studies have described that electrical stimulation of the vagus nerve, in conditions of slight hyperglycemia, stimulates its release from the β-cells." (PMID 32232085, 2018). "Previously, we demonstrated that a LOAEL dose of Cd in drinking water produces a metabolic toxicity that is characterized by insulin resistance in multiple peripheral tissues, increasing insulin release with hyperglycemia and lipid metabolism alterations." (PMID 30201894, 2018). "The patient received ursodeoxycholic acid for PSC, cholestyramine, an antihistamine and an SSRI for treatment of pruritus, along with insulin for hyperglycemia." (PMID 30132197, 2018). "It has been demonstrated that HFD impairs hepatic insulin signaling via CB1R activation, which contributes to insulin resistance and gluconeogenesis, resulting in hyperglycemia." (PMID 29570673, 2018). "It has also been demonstrated that C3G significantly ameliorated hyperglycemia and insulin sensitivity in vivo." (PMID 30564116, 2018). "Protein O-GlcNAcylation increases in diabetic tissues and hyperglycemia drives excessive chronic O-GlcNAcylation of proteins, including those involved in insulin signaling in DM." (PMID 29315243, 2018). "Although hyperglycaemia is usually managed with continuous insulin infusion, the optimal management of plasma glucose in STEMI patients with SH remains an open question." (PMID 30259778, 2018). "Hyperlipidemia alone or in concert with hyperglycemia, termed as “lipoglucotoxicity” can induce a pro-inflammatory state, shown in fat, where elevated free fatty acids lead to impaired insulin sensitivity." (PMID 29426925, 2018).
Hyperglycemia (continued). "All enrolled patients developed hyperglycemia and required insulin treatment, after surgery and intra-operative radiation therapy." (PMID 29300728, 2018). "It should be noted that in the NICE‐SUGAR study, the control group was also treated with insulin to keep glycemic levels between 140 and 180 mg/dl, instead of the uncontrolled hyperglycemia (up to 215 mg/dl) in the first studies." (PMID 29976786, 2018). "When T2D progresses, total insulin secretion becomes insufficient leading to significant hyperglycemia." (PMID 29587416, 2018). "When hyperglycemia isfirst discovered in the perioperative period, if insulin is administered for thefirst time, or when a new insulin protocol is instituted, the patient shouldreceive expert advice before discharge." (PMID 30652752, 2018). "Although exhaustive exercise protected against olanzapine-induced hyperglycemia in IL-6−/− mice, we found that exercise-induced increases in serum insulin from olanzapine compared to vehicle treated animals were absent." (PMID 29335597, 2018). "A hydrolysate prepared by bovine casein attenuated nod-like receptor protein 3 (NLRP3) activity and improved insulin signaling, resulting in reduced hyperglycemia and inflammation in mice fed with HFD." (PMID 29473848, 2018). "Romifidine induced hyperglycaemia, which vatinoxan partially prevented despite of the variations in baseline levels of serum insulin." (PMID 29743097, 2018). "Mainly characterized by hyperglycemia due to resistance to insulin, the disease mechanism of T2D involves a combination of multiple genetic and dietary factors." (PMID 29932108, 2018). "It was first described more than four decades ago, with hyperglycemia and impaired cardiac insulin signaling pathway having pivotal roles in its progression/onset." (PMID 30425649, 2018). "In vitro and murine studies have shown that the overactivity of the potassium channels from overexpression of KCNQ1 can create a current across the plasma membrane and impair insulin secretion, thereby resulting in hyperglycemia." (PMID 30369944, 2018). "The process of destruction of pancreatic β cells, called insulitis, is a consequence of an immunological attack mediated by lymphocytes, macrophages and NK cells and leads to a permanent hyperglycemia and the need for exogenous insulin replacement." (PMID 30254638, 2018). "Conversely, during the postprandial period, elevated GIP and GLP-1 levels augment postprandial insulin secretion to prevent hyperglycaemia." (PMID 30662430, 2018). "At the end of experiments, hyperglycemia, insulin resistance variables, lipid profile, hepatic enzymes, liver mitochondrial oxidative stress, islet insulin secretion, liver, and pancreas histopathology were evaluated in all mice by their own methods." (PMID 29755549, 2018). "Adipose defects observed in the F-BCA mice mimic lipodystrophy, a disorder accompanied by metabolic disturbances, including hyperglycemia, insulin resistance, and ectopic lipid deposition in secondary organs." (PMID 30080858, 2018). "DPP-IV inhibitors shorten the inactivation of GLP-1, permitting the incretin to stimulate insulin release, thereby combating hyperglycemia." (PMID 30103438, 2018). "The first step to fully closing the loop in the AP requires removing meal announcement, which is currently the most effective way to alleviate postprandial hyperglycemia due to the delay in insulin action." (PMID 29547553, 2018). "HFD feeding induced hyperglycemia and increases in plasma insulin and leptin levels, whereas plasma triglyceride were unchanged." (PMID 29686414, 2018). "In the early stage, the persistence of hyperglycemia and hyperlipidemia will aggravate IR and further weaken the function of insulin secretion, which are displayed as the reduction of insulin secretion and the decrease of pancreatic β cells." (PMID 30356368, 2018).
Hyperglycemia (continued). "We used Streptozotocin (STZ) as a chemical that selectively destroys the insulin secreting islet β-cells in the pancreas to induce hyperglycemia as a way to elevate blood sugars and test for glucose utilization." (PMID 29951281, 2018). "In most cases, this hyperglycemia is the result of impaired glucose tolerance due to pancreatic β-cell dysfunction on a background of chronic insulin resistance." (PMID 30373146, 2018). "In the hospital setting, premixed insulin was reported to be effective in improving hyperglycemia and controlling HbA1c in T2DM inpatients, and the effect was also similar to inpatients receiving basal insulin." (PMID 30420835, 2018). "Major trauma or full-thickness burn injury can induce significant metabolic dysfunction (hyperglycemia, insulin resistance, lactate production) which contributes to inflammation, increased catabolism, and ultimately muscle wasting." (PMID 29298131, 2018). "Of the 343 patients exhibiting hyperglycemia upon admission, 88% were continuously monitored and 77.8% received hypoglycemic therapy, mostly as insulin." (PMID 30619050, 2018). "Maternal hyperglycemia occurs when insulin secretion from pancreatic β cells is inadequate for the increased insulin requirements during pregnancy." (PMID 30081861, 2018). "Over time, the disruption in insulin signaling gives way to chronic hyperglycemia and, eventually, full-blown T2DM." (PMID 29770126, 2018). "We found that intermittent leucine deprivation is able to significant reduce hyperglycemia in db/db mice, accompanied by significant improvement in glucose tolerance and insulin sensitivity." (PMID 30294696, 2018). "Metabolic syndrome and the resulting insulin and leptin resistance and hyperglycemia have pro-inflammatory effects with profound consequences on the BBB." (PMID 30618559, 2018). "The ADA guidelines suggest hyperglycemia to be treated as early as possible, even with insulin in specific cases, to address T2DM individualized targets." (PMID 30327785, 2018). "Mouse and human hepatic stem cells were differentiated into insulin-secreting β-like cells and used to overcome the condition of hyperglycemia." (PMID 30046616, 2018). "The first step to closing the loop is removing meal announcement; however, many challenges still remain due to the insulin action lag time and the discrepancy in postprandial hyperglycemia, which is dependent on meal composition and intra-patient variability." (PMID 29547553, 2018). "For instance, orthopedic patients had less hyperglycemia than general surgery patients, but they also had lower odds of receiving basal-bolus insulin therapy." (PMID 29255628, 2018). "In this vein, an insulin resistant state is defined as the impairment of glucose uptake in muscle and an increased gluconeogenesis by the liver resulting in hyperglycemia, both in fasting and postprandial states." (PMID 30170598, 2018). "Insulin is generally considered to have vasodilator effects, so if plasma insulin influenced the study, it likely acted to limit the vasoconstrictive effect of hyperglycemia by the endogenous postprandial rise in insulin secretion." (PMID 30319819, 2018). "Most significantly, we uncovered an insulin-independent beneficial role for androgen receptor antagonism in hyperglycemia, mostly by reducing fasting glucose levels." (PMID 30520733, 2018). "In this regard, while there is evidence that opium consumption is the cause of impaired glucose tolerance and increased resistance to insulin, other studies have also shown severe hyperglycaemia following the discontinuation of opium." (PMID 30501025, 2018). "At our institution, the use of metformin for the treatment of GDM has been adopted as an alternative approach to insulin therapy in the management of hyperglycaemia in this population of women." (PMID 29522471, 2018). "Hyperglycemia has been also shown to augment indices of arterial stiffness, especially in people with reduced insulin sensitivity and in patients with T2DM." (PMID 30231923, 2018).